CD44 (CD44 molecule (IN blood group))
Diseases named in the same sentence as CD44 in open-access papers (continued):
Sharing a sentence is not in itself a finding about the gene and the disease.
lung carcinoma (continued). "Thus, a single marker may not be sufficient to isolate CSCs, and as a result, several markers are employed together to isolate certain types of CSCs, such as CD44+CD133+CD24+ cancer stem-like cells involved in murine melanoma, CD133+CD34+ melanoma CSCs, and CD133+/nestin+ lung cancer CSCs." (PMID 22558209, 2012). "Quantitative gene expression of SPP1, VEGFA, POSTN, RUNX2, CD44, and FOXO1 from lung cancer patients with and without bone metastasis normalized against healthy control." (PMID 36424413, 2022). "The expression levels of CD44, SOX2, Nanog, Oct4, and ABCG2 in lung cancer nodules from Tumor + CIH groups were significantly upregulated compared with the lung cancer tissues from Tumor + Nor mice." (PMID 33596919, 2021). "For instance, in breast and lung cancers, the introduction of ESRP1 prompted the splicing switch from CD44s to CD44v8-10 with no change in the total amount of CD44." (PMID 34944493, 2021). "In this study, our results showed that the mRNA levels of Bmi1, CD44 and CD133 were not significantly different between lung cancer and non-malignant lung tissues." (PMID 23683495, 2013). "In this study, we applied RT-PCR to examine the differential expression of Bmi1, CD133, CD44, Sox2, Nanog, OCT4 and Msi2 mRNA in bronchoscopic biopsy specimens from lung cancer and non-cancer patients." (PMID 23683495, 2013). "Using the CD44‐negative normal human lung cells (HFL1) and human lung cancer cells (A549) known to express CD44, we found that the IGFBP‐3 l‐peptide, but not its mutant, reduces A549 cell viability by disrupting HA‐CD44 interactions, a result consistent with our previous reports." (PMID 32592613, 2020). "However, the positive expression rates of CD133, CD44, Sox2, OCT4 and Msi2 did not correlate with age, gender, histological type, stage and differentiation of lung cancer." (PMID 23683495, 2013). "Our study does not show that all CD44+ cells are bona fide CSC, however, we propose that CD44 could be a marker of tumor initiation ability in some lung cancer cells." (PMID 21124918, 2010).
glioblastoma (240 papers, 2008 to 2025). The most malignant astrocytic tumor (WHO grade IV). "These CAR-T cells are believed to have immunostimulating and anti-neoplastic activities since they target CD133 and CD44, two markers of GSCs, associated with the proliferative or invasive state of glioblastoma cells." (PMID 41208963, 2025). "In support of this, it has also been shown in glioblastoma that bevacizumab failure is associated with CD44 expression." (PMID 40140675, 2025). "Previously, TGF-β signalling activity has been found to be upregulated in perivascular niches and closely associated with stemness markers such as Id1, CD44, Sox4 and Sox2, suggesting an underlying inherent plasticity of glioblastoma tumour cells." (PMID 39724753, 2024). "The content of EVs in biofluids, including subtype-specific markers like CD44, provides valuable information about the phenotype of glioblastoma and can serve as diagnostic and personalized treatment indicators." (PMID 37568620, 2023). "This is in agreement with a recent study suggesting that the correlation between poor prognosis and high CD44 levels in glioblastoma is linked to the presence of CD44-expressing GAMs and to their pro-tumorigenic transformation." (PMID 35992852, 2022). "CD44 distribution outside the lipid raft of human glioblastoma cells has been shown to induce metalloproteinase‐mediated CD44‐associated cell migration." (PMID 34939255, 2022). "Depletion of CD44 in U251MG glioblastoma cells caused decreased proliferation and stemness, and acquisition of a pro-senescence state." (PMID 35954411, 2022). "Several reports linked glioblastoma progression with HA levels and even with CD44 and RHAMM expression, as well as MEK/ERK activation." (PMID 34628469, 2021). "Other markers (e.g., CD133, CD44) have been shown to be associated with stem cell ability in glioblastoma, and it would be interesting to evaluate their expression patterns in PDXs." (PMID 32260145, 2020). "In order to specifically isolate relevant glioblastoma-associated EVs, we subsequently performed immunoprecipitation using CD44 (SEC + CD44), which we had previously identified in a screen of serum EV proteins as being important in tumor progression." (PMID 33003586, 2020). "In general, high CD44 expression is linked to mesenchymal subtype of glioblastoma and this associates with poor prognosis." (PMID 29914429, 2018). "The results may include specific markers, like glioblastoma-specific CD44 variants (and Eibl, unpublished) since they don’t express the epithelial marker often used for many other cancers." (PMID 41514523, 2025). "For example, PTEN-deficient glioblastomas overexpress CD44 cell-surface adhesion receptors and have a tighter tumor cell phenotype than wild-type glioblastomas, which can exclude angioforming and immune cells in TME, making them less responsive to immune checkpoint inhibitors (ICI)." (PMID 39206155, 2024). "CD44 is not only expressed by cancer cells, particularly cancer stem cells, but also in cell types from the glioblastoma TME, including high-grade GBM-associated astrocytes, endothelial cells, resident and infiltrating immune cells like microglia, macrophages and T lymphocytes." (PMID 35992852, 2022). "As discussed, increased RFX1 expression was associated with CD44 down-regulation in glioblastoma." (PMID 33964962, 2021). "In addition, CD44 was implicated in the formation of invadopodia-like protrusions in glioblastoma CSCs by mediating ECM sensing." (PMID 30736372, 2019). "Its mapping of co‐expression combinatorics and its finding of a CD44+/CD133+/ITGA6+/CD36+ molecule signature on gliomaspheres is a relevant step towards a more complete understanding of stemness‐associated molecules in glioblastoma." (PMID 30467961, 2019). "To further investigate whether galangin causes anti-EMT effects via the inhibition of CD44 in glioblastoma cells, we generated transfected U87 and U251 cell lines overexpressing CD44 by transfecting the cells with a CD44 cDNA plasmid." (PMID 31528214, 2019).
glioblastoma (continued). "It was found that NF-κB activation caused both MES differentiation and CD44+ expression in GSCs, suggesting that NF-κB-targeted therapies may be effective to increase radiosensitivity in this particular glioblastoma subtype." (PMID 29246031, 2017). "Studies in glioblastoma multiforme (GBM), an invasive brain tumor associated with abnormal HA secretion, tissue stiffening, and CD44 overexpression, showed upregulation of the transcripts related to HA/CD44 adhesion." (PMID 39334952, 2024). "Moreover, all glioblastomas expressed CD44 variants (CD44v3–CD44v10) whereas expression in astrocytomas WHO grade I, II and III could only be detected in only 50 % of the tumor samples." (PMID 37298284, 2023). "The results revealed that glioblastomas of ArMRS high-risk group had significantly higher expression levels of CD44, CD48, CD276 (B7-H3), and PD1 (PDCD1) compared to low-risk group in the TCGA cohort, suggesting higher ArMRS may indicate more abundant expression of immunotherapy targets." (PMID 37214463, 2023). "Here, we demonstrate the presence and function of the variant form 6 of CD44 (CD44v6) in BTSC of a subset of glioblastoma multiforme (GBM)." (PMID 21915300, 2011). "CD44 is a stem cell marker in mesenchymal-type glioblastomas, the most aggressive type of glioblastoma." (PMID 40430568, 2025). "Research using these models has revealed critical insights into the mechanisms of glioblastoma invasiveness, such as the role of integrin and CD44-mediated pathways and identified potential therapeutic targets like Lck." (PMID 40940872, 2025). "The activation of EGFR was shown to be accompanied by the upregulation of CD44 expression and the enhancement of the migratory and invasive capabilities of glioblastoma cells." (PMID 40227788, 2025). "Their study employed microscopy techniques to observe the interaction between tumor cells and brain tissue, revealing that glioblastoma cells use specific integrin and CD44-mediated pathways to propel themselves through the tissue." (PMID 40940872, 2025). "More importantly, the intratumor activation of the mitogen-activated protein kinases (MAPKs) and the PI3K/protein kinase B (AKT) pathways participate in the role and mechanism of the CD44 in the glioblastoma tissue." (PMID 40607003, 2025). "Interactions between the EGFR and CD44 were reported to play a significant role in the pathology of glioblastoma." (PMID 40227788, 2025). "In recent years, the interplay between members of the HER family receptors with EGFRvIII and cancer stem cell biomarkers like CD44 and CD109 have been associated with the aggressive nature of glioblastoma." (PMID 40227788, 2025). "Review papers featuring developments related to the therapeutic implications of CD44, its role in chemoresistance and metastasis, its potential role in diagnosis, and its role in glioblastoma multiforme have been published." (PMID 41440277, 2025). "Recent studies have confirmed that RFX1 directly reduces CD44 expression and inhibits glioblastoma invasion, suggesting the importance of RFX1 in tumor physiology." (PMID 41425715, 2025). "Investigation of proteins inside extracellular vesicles from glioblastoma patients revealed the upregulation of 6 proteins, including CD44, compared with those in healthy volunteers." (PMID 41440277, 2025). "For example, glioblastoma multiforme, one of the most malignant brain tumors, expresses high levels of the HA receptor CD44." (PMID 41440277, 2025). "We also find myosin, integrins and CD44 to be important for cell migration, with implications for therapeutic targeting of glioblastoma cell migration." (PMID 38737451, 2024). "We find that treatment of glioblastoma via targeting migration should either simultaneously target both integrins and CD44, or else target myosin II." (PMID 38737451, 2024). "The usefulness of CD44 in evaluating the therapeutic responses of targeted therapy has been analyzed in glioblastoma multiform (GMB)." (PMID 38672650, 2024).
glioblastoma (continued). "In glioblastoma multiforme cells, high expression of CD44 was found to induce cancer stemness and EMT features via KRAS/ERK signaling activation." (PMID 38783892, 2024). "One of the studies on glioblastoma demonstrated that the periphery/core (P/C) ratio of the CD44 expression in glioblastoma was significantly correlated with responsiveness to the angiogenic inhibitor, Bevacizumab, in the treatment of recurrent tumors." (PMID 39768912, 2024). "Overall we find that glioblastoma cell migration is most consistent with a motor-clutch mechanism to migrate through brain tissue ex vivo, and that both integrins and CD44, as well as myosin motors, play an important role in constituting the adhesive clutch." (PMID 38737451, 2024). "While comparisons are frequently made between PMT and EMT, the naming of the mesenchymal glioblastoma subtype was based largely on the two markers CD44 and MERTK, with the latter being an unconventional mesenchymal marker." (PMID 38337036, 2024). "All primary glioblastoma cultures showed 91.2–99.3% expression of the cancer cell marker CD44, which is overexpressed in GBM, and 6.8–61.6% expression of GFAP, which is expressed by astrocytes and in astrocytic brain tumors." (PMID 36902447, 2023). "CAFs were also noted to be in close proximity to cells expressing glioblastoma stem cell (GSC) marker CD44 and were enriched in the perivascular niche where GSCs reside based on their proximity to endothelial cells expressing CD34 or CDH5." (PMID 36856115, 2023). "For example, it has been shown that CD44 inhibition in the U251 glioblastoma cell line reduced migration and invasion ability in transwell assays, while its re-expression re-established the high migratory and invasive phenotype." (PMID 37511533, 2023). "In fatal brain tumors, lactate-driven upregulation of malignant glioblastoma cells (GM) promoted the release of CD44-rich exosomes, increased GM migration and endothelial cell formation, and secreted exosomes." (PMID 37210528, 2023). "Xu and colleagues demonstrated that CD44 depletion in glioblastoma cells is responsible for activating the Hippo pathway, inhibiting tumor growth in vivo and in vitro, as well as sensitizing glioblastoma to temozolomide treatment." (PMID 37366874, 2023). "The one-year survival rate is significantly lower for patients with glioblastoma multiforme displaying high CD44 immunostaining." (PMID 36835465, 2023). "According to the Ivy Glioblastoma Atlas Project data, in peri-necrotic zones, pseudo palisading cells around necrosis, cellular tumors, and hyperplastic blood vessels, CD44 was highly expressed." (PMID 36776876, 2023). "IQGAP1 couples HA/CD44 to cytoskeletal functions in other cells: IQGAP1 promotes HA-induced migration and proliferation of fibroblasts and CD44-mediated adhesion of glioblastoma cells to HA-rich ECM." (PMID 37071417, 2023). "Recently, it was reported that chitinase 3-like 1 (Chi3l1) binds to CD44 and induces the phosphorylation of β-catenin at Ser552 by Akt in glioblastomas and TANK-binding kinase 1 (TBK1) in cholangiocarcinomas, leading to its nuclear translocation." (PMID 38136210, 2023). "In glioblastoma, CD44 downregulation prevents tumor growth and sensitizes cancer cells to cytotoxic drugs." (PMID 35625673, 2022). "For example, the migration and survival of glioblastoma cells are dependent on CD44 but follow a biphasic response profile in both mice and humans." (PMID 35568736, 2022). "In glioblastoma, it was found to promote the expression of stem cell marker CD44 by impairing miRNA function." (PMID 36551712, 2022). "As a glycoprotein, a high expression level of CD44 is associated with poor prognosis of cancer patients, including head and neck squamous cell carcinoma (HNSCC), glioblastoma, and hepatocellular carcinoma." (PMID 35669102, 2022).
glioblastoma (continued). "Here, we confirmed that interfering with HA synthesis in glioblastoma cells or blocking the binding of HA to CD44 on macrophages induced macrophages polarization toward the M1 phenotype, and the induced macrophages showed a therapeutic effect for glioblastoma." (PMID 35410993, 2022). "In this work, we aimed to clarify the role of the transmembrane glycoprotein CD44 in the cross-talk between malignant cells and the glioblastoma microenvironment." (PMID 35992852, 2022). "The expressions of the cell-surface glycoproteins (i.e., CD44) act as the leading targeting approaches against glioblastoma using liposome NPs." (PMID 35163563, 2022). "Sevoflurane increased the migration and colony formation of human glioblastoma cells via the expression of CD44." (PMID 35222023, 2022). "CD44 is a transmembrane adhesion glycoprotein and was indicated to be a promising predictor for poor prognosis in glioblastoma multiforme (GBM)." (PMID 36217151, 2022). "CD133 is an established indicator of stemness in glioblastoma and its expression with CD44 has been demonstrated previously to drive expansion of TICs37,38." (PMID 35840697, 2022). "Accordingly, antibody (against glioblastoma stem cells surface markers glycoprotein cluster of differentiation 44 (CD44) and ephrin receptor A2 (EPHA2)-antisense oligodeoxynucleotides (ASOs) strategy against FAM107A) were established for the treatment of GBM." (PMID 33804473, 2021). "Other important ECM-binding proteins and/or modifying enzymes in glioblastoma cells are CD44 (HA receptor), matrix metalloproteinase-9 (MMP9), and hyaluronidases 1/2/3 (Hyal 1/2/3)." (PMID 34070023, 2021). "RFX1 also prevented the metastasis of multiple glioblastoma cell lines via down-regulating CD44 expression." (PMID 33964962, 2021). "The hyaluronic acid receptor CD44 that has been shown to be upregulated in glioblastoma compared to LG astrocytoma was unexpectedly overexpressed in DIS6." (PMID 33853673, 2021). "Interest in CD44 in EVs has been stimulated by the finding that CD44-containing EVs serve as a biomarker for glioblastoma." (PMID 34576260, 2021). "OMICS studies have identified CD44 to be overexpressed in many types of cancer including glioblastoma." (PMID 34301218, 2021). "RFX1 itself is a relevant tumor suppressor transcription factor in glioblastoma due to its negative regulation of CD44 expression." (PMID 33964962, 2021). "Localization of CD44 outside lipid rafts in human glioblastoma allows metalloproteinase-mediated CD44 shedding and tumor cell migration while raft disruption by cyclodestrins or simvastatin increase CD44 shedding and migration." (PMID 33450869, 2021). "CD44 inhibition by miR-138 resulted in an inhibition of glioblastoma cell proliferation in vitro through cell cycle arrest as evidenced by a significant induction of p27 and its translocation into nucleus." (PMID 33911148, 2021). "In another study, depletion of CD44 was shown to block glioblastoma growth and sensitizes glioblastoma cells to cytotoxic drugs in vivo, and CD44 functions upstream of the mammalian Hippo signaling pathway in glioblastoma cells." (PMID 32232385, 2020). "CD44 can also be found on EVs from different non-malignant cells, such as B- or T-cells, thus, we cannot exclude the possibility that some non-glioblastoma EVs are found in our SEC + CD44 EV fractions." (PMID 33003586, 2020). "We have previously identified a key role for CD44, found on the surface of serum-EVs from glioblastoma patients, in the detection of tumor progression." (PMID 33003586, 2020). "Combining miR-15b-3p in serum or miR-106a-5p in SEC + CD44 EVs with any one of the other three microRNAs in SEC + CD44 EVs allowed for a prognostic stratification of glioblastoma patients." (PMID 33003586, 2020).